TNFSF10 (TNF superfamily member 10)
Diseases named in the same sentence as TNFSF10 in open-access papers (continued):
Sharing a sentence is not in itself a finding about the gene and the disease.
COVID-19 (37 papers, 2020 to 2025). A disease caused by infection with severe acute respiratory syndrome coronavirus 2. "S100A9 was upregulated only in adults with severe COVID-19, while upregulation of TNFSF10 (TRAIL) was correlated with p-PB, indicating more robust inflammation in these groups." (PMID 37638019, 2023). "IFITM2 and TNFSF10 were the two DEGs that overlapped when comparing the gene expression levels from patients of COVID-19, cancer, ARDs and PF." (PMID 36555339, 2022). "Specifically, changes in the expression level of TNFSF10 in monocytes can be considered as an immune signature in COVID-19 patients with hematologic cancer." (PMID 36555339, 2022). "We also found that TNFSF10 as an immune-related gene was upregulated in COVID-19 patients with cancer." (PMID 36555339, 2022). "The presence of cytotoxic lymphocytes and elevated expression of TRAIL (TNFSF10) suggests that severe lung damage in COVID-19 may involve cytolysis and extrinsically regulated apoptosis." (PMID 36472908, 2023). "Our study found that COVID-19 patients have upregulated pathways in apoptotic signaling pathways and response to virus/viral process, including genes TNF, TNFAIP3, TNFSF10, TNFRSF1B, TNFRSF1." (PMID 37949875, 2023). "Based on the PBMC samples from the cellxgene dataset, the expression data of TNFSF10 and IFITM2 in COVID-19 patients were obtained by Single-cell RNA-seq analysis." (PMID 36555339, 2022). "Targeting TNFSF10 and IFITM2 in CD14+ and CD16+ monocytes may affect the immune response of COVID-19 patients with cancer." (PMID 36555339, 2022). "Changes in the expression levels of TNFSF10 and IFITM2 in CD14+/CD16+ monocytes may affect the immune response of COVID-19 patients." (PMID 36555339, 2022). "Based on the GSE153610 dataset, compared with recovered COVID-19 patients without cancer, TNFSF10 were upregulated in monocytes of cancer patients infected with SARS-CoV-2, while IFITM2 were downregulated." (PMID 36555339, 2022). "Furthermore, expression levels of genes controlling cell proliferation and apoptosis, such as TGFB1, CDK4, TNFSF10, and TNFRSF10A, were also found to be dysregulated in CD4+ T cells of patients who recovered from COVID-19." (PMID 34784300, 2021). "Additionally, we found that PCs in patients with severe COVID-19 had higher expression levels of inflammation genes (TNFSF10, S100A9, and S100A8) and chemokine-related genes (CCR2 and ITGB7) than those in patients with mild COVID-19." (PMID 33936072, 2021). "Among others, cytokine-related genes IL12B and TNFSF10 and members of the Krüppel-like factors (KLF) and CCAAT/enhancer-binding protein (CEBP) family of transcription factors as well as transcription factor 7 (TCF7) were affected only in COVID-19-derived PBMCs." (PMID 37614228, 2023). "In addition, the common DEGs among ARDS, PF and COVID-19 patients with and without cancer are TNFSF10 and IFITM2." (PMID 36555339, 2022).
autoimmune disease (36 papers, 2010 to 2025). A disorder resulting from loss of function or tissue destruction of an organ or multiple organs, arising from humoral or cellular immune responses of the individual to their own tissue constituents. "Tumor necrosis factor (TNF) related to apoptosis-inducing ligand (TRAIL/Apo2L/TNFSF10) is a member of the TNF super family of proteins involved in cancer development and autoimmune diseases, and is expressed in human and rodent testis, including germ cells, Sertoli cells, and Leydig cells." (PMID 24736722, 2014).
triple-negative breast carcinoma (31 papers, 2014 to 2026). An invasive breast carcinoma which is negative for expression of estrogen receptor (ER), progesterone receptor (PR), and human epidermal growth factor receptor 2 (HER2). "The findings of Yoo Jane Han suggest that TNFSF10 plays an important role in regulating the antiviral immune response in triple-negative breast cancer (TNBC)." (PMID 38285218, 2024).
Sepsis (30 papers, 2013 to 2025). Sepsis is defined as life-threatening organ dysfunction caused by a dysregulated host response to infection. "Elevated TNFSF10 expression was associated with increased immune cell apoptosis, a hallmark of the immunosuppressive phase of sepsis." (PMID 40362669, 2025). "Receiver operating characteristics show that key genes such as TMCC2 (AUC = 0.973), TNFSF10 (AUC = 0.969), and PLVAP (AUC = 0.897) demonstrate high predictive accuracy for sepsis progression, underscoring their potential as diagnostic biomarkers." (PMID 40362669, 2025). "Up-regulating miR-24-3p from M2-exo imposes cardioprotection against myocardial injury after sepsis through reducing Tnfsf10 expression." (PMID 40041174, 2025). "Key genes like TNFSF10, TMCC2, and PLVAP genes show strong diagnostic potential, providing novel insights into sepsis pathogenesis and offering promising targets for future therapeutic interventions." (PMID 40362669, 2025). "The upregulated miR-24-3p in macrophage-derived M2 exosomes improves cardioprotection after myocardial injury in sepsis by decreasing Tnfsf10 expression, positioning miR-24-3p as a potential sepsis biomarker." (PMID 39104595, 2024). "It has been reported that the upregulation of miRNA-24-3p in M2 macrophage-derived exosomes reduced the expression of tumor necrosis factor superfamily member 10 (TNFSF10), thereby exerting a cardioprotective effect on myocardial injury after sepsis." (PMID 35326456, 2022). "In contrast, recent literature highlights the concept that M2-exosomes-derived miR-24-3p targets the TNFα superfamily member Tnfsf10 (TRAIL) to reduce myocardial injury after sepsis, improving cardiac function." (PMID 35406812, 2022). "Notably, TNFSF10, GUCD1, and PLVAP show strong associations with pathways sepsis-relevant sepsis development." (PMID 40362669, 2025). "In conclusion, our integrative approach identified several robust gene signatures, including TNFSF10, PLVAP, and TMCC2, as potential biomarkers of sepsis severity." (PMID 40362669, 2025). "Although the present study is limited by the lack of experimental validation, future work will incorporate qPCR, Western blotting, and functional assays to confirm the expression and biological roles of TNFSF10, TMCC2, and PLVAP in sepsis." (PMID 40362669, 2025). "The correlation matrix highlights strong positive relationships among key genes such as TNFSF10, EPB41, PLVAP, and TMCC2, suggesting their coordinated involvement in sepsis pathogenesis." (PMID 40362669, 2025). "Receiver operating characteristic (ROC) analysis demonstrated high predictive accuracy for sepsis progression, with AUC values of 0.973 (TMCC2), 0.969 (TNFSF10), and 0.897 (PLVAP)." (PMID 40362669, 2025). "A PPI network identified key hub genes, including IGLL5, BCL2L1, TNFSF10, and SNCA, with significant connections, highlighting their critical roles in sepsis development and potential as biomarkers or therapeutic targets." (PMID 40362669, 2025). "To refine candidate selection, we implemented machine learning algorithms (random forest and SVM-RFE), which robustly identified TMCC2, TNFSF10, and CTNNA1 as key predictors of sepsis severity." (PMID 40362669, 2025). "TNFSF10 (TRAIL) and S100A8/9, were found to be significantly upregulated in late sepsis CD4+ and CD8+ T- lymphocyte subsets, respectively." (PMID 34484194, 2021). "Genes such as TMC2, TNFSF10, and CTNNA1 were the most significant predictors of sepsis severity." (PMID 40362669, 2025).
Obesity (29 papers, 2013 to 2025). Accumulation of substantial excess body fat. "Specifically, we detected down-regulation of HLA-DRA (1.38-fold), STAT1 (1.3-fold), TNFSF10 (1.7-fold), and FCGR3A (fold reduction 1.65) with pregravid obesity." (PMID 34195568, 2021).
osteosarcoma (28 papers, 2003 to 2025). A usually aggressive malignant bone-forming mesenchymal neoplasm, predominantly affecting adolescents and young adults. "Numerous studies have reported an association between TNFSF10 and the progression of osteosarcoma." (PMID 38285218, 2024).
breast tumor (23 papers, 2003 to 2026). "We found the SNP served as an enhancer variant and regulated TNFSF10 (TRAIL) expression in TNBC cells, with a significant association between the SNP genotype and TNFSF10 expression in breast tumors." (PMID 35930348, 2023).
pancreatic ductal adenocarcinoma (22 papers, 2010 to 2026). An infiltrating adenocarcinoma that arises from the epithelial cells of the pancreas. "A previous study showed that TNFSF10 stimulation of pancreatic ductal adenocarcinoma (PDAC) cells induced the secretion of CXCL8, and the expression of CXCL8 correlated with the concentration of TNFSF10 added to the cells." (PMID 38405671, 2024).
rheumatoid arthritis (22 papers, 2006 to 2026). A chronic, systemic autoimmune disorder characterized by inflammation in the synovial membranes and articular surfaces. "For rheumatoid arthritis, systemic lupus erythematosus, ankylosing spondylitis and osteoarthritis diseases, those common factors include TNFSF10, CX3CR1, LY96, TLR5, TXN, TIA1, PRKCH, and PRF1." (PMID 26352601, 2015).
acute myocardial infarction (19 papers, 2009 to 2025). Necrosis of the myocardium, as a result of interruption of the blood supply to the area. "Interestingly, TNFSF10, TNFSF11, and MCP-2 levels were lower in STEMI patients than in controls, which may reflect the complex regulatory mechanisms involved in inflammation and immune response following myocardial infarction." (PMID 39955425, 2025).
Alzheimer disease (17 papers, 2016 to 2025). A progressive, neurodegenerative disease characterized by loss of function and death of nerve cells in several areas of the brain leading to loss of cognitive function such as memory and language. "Research on Alzheimer’s disease has shown TNFSF10’s association with inflammatory responses and cognitive decline, with neutralization of TNFSF10 significantly restoring cognitive behavior and reducing inflammatory mediators in tissues." (PMID 41021615, 2025). "A similar pattern has been shown in other pathological situations such as in the advanced stage of Alzheimer’s disease, where TNFSF10 secreted by astrocytes binds to TNFRSF10B on neurons and triggers caspase-8-dependent apoptosis." (PMID 34835061, 2021). "It has been shown that neutralization of TNFSF10 ameliorates functional outcome in a murine model of Alzheimer’s disease." (PMID 32438758, 2020). "We have also measured the levels of TNFSF10 (TRAIL), which has been associated with neuroinflammation in adult neurodegenerative diseases including Alzheimer’s disease and multiple sclerosis." (PMID 32024172, 2020).
heart failure (17 papers, 2009 to 2025). Inability of the heart to pump blood at an adequate rate to meet tissue metabolic requirements. "A low TNFSF10 level is an indicator of heart failure and poor prognosis." (PMID 38145212, 2023). "Recently, death receptor (DR; also called TRAIL-R2, TNFRSF10B) 5 and its ligand, TNF-Related Apoptosis-Inducing Ligand (TRAIL; also called Tnfsf10, APO2L, and CD253), have been linked to multiple forms of human heart failure, although the function of DR5 in the heart is poorly understood." (PMID 34527710, 2021). "Correlation analysis showed that TNFSF10 was positively correlated with the expression of homocysteine, COL1α2 and BDNF, while negatively correlated with EF, suggesting that TNFSF10 might be associated with heart failure." (PMID 38145212, 2023).
Stroke (17 papers, 2015 to 2025). Sudden impairment of blood flow to a part of the brain due to occlusion or rupture of an artery to the brain. "The key genes encompass critical pathways such as autophagy (e.g. NFE2L2, DDIT3, NAMPT), apoptosis (e.g. CFLAR, FADD) and NF-κB signaling (e.g. RELA, TNFSF10), suggesting a multifactorial involvement of these pathways in stroke pathophysiology." (PMID 40969765, 2025). "Flowchart illustrating the protective effect of zinc on stroke through various stages: GWAS analysis and NHANEs database, bioinformatic analysis, diagnostic model, pathway analysis showing autophagy, and genes involved (RELA, TNFSF10, NFE2L2, FADD, DDIT3, CFLAR)." (PMID 40969765, 2025). "Genes related to inflammation such as Ccl5, Cxcl5, Il1a, Tnfsf10, Nfkb1, Tnfrsf1b, Ccr7, Tnfrsf9, Ccl7, Il1b, Il6, and Ccl24 were also downregulated upon MMP-3 KO in male stroke brains." (PMID 39000490, 2024).
ischemic stroke (16 papers, 2018 to 2025). A stroke disorder caused by obstruction of blood flow to the brain, due to thrombotic (local blood clot formation) or embolic (due to a blood clot or other material traveling from another site) event. "This appears in line with other data, showing an increase of TNFSF10 and its death receptor in different neurodegenerative processes, occurring, for example, after spinal cord injury, and in the post-ischemic stroke." (PMID 34611142, 2021).
cholangiocarcinoma (13 papers, 2006 to 2024). A carcinoma that arises from the intrahepatic biliary tree (intrahepatic cholangiocarcinoma) or from the junction, or adjacent to the junction, of the right and left hepatic ducts (hilar cholangiocarcinoma). "Finally, an anti-tumor activity of TRAIL/TNFSF10 in cholangiocarcinoma can also rely on additional mechanisms, namely activation of other TRAIL receptors than TRAIL-R1/TNFRSF10A, and targeting of other tumor promoting cells than just the tumor cells." (PMID 37404757, 2023).
Hepatitis (13 papers, 2012 to 2024). Inflammation of the liver. "Interestingly, quantities of Fasl, Fas, Tnfsf10 [TRAIL], and Tnfrsf10b [TRAIL-R2] mRNAs were over-induced especially in Ripk1LPC-KO in presence of ETA, which correlated with the worsening of hepatitis." (PMID 35806372, 2022).
lupus (12 papers, 2009 to 2025). "Besides FOS, FOXO1, and FOXO3, upregulated TBK1 and TNFSF10 contributed to the activation prediction of ‘Systemic Lupus Erythematosus In B Cell Signaling’." (PMID 35406685, 2022). "Finally, we verified the expression of TNFSF10 and MAP1LC3B in a lupus mice model." (PMID 39869603, 2025). "Together, common characteristics of lupus appear to be upregulation of members of the IL-1 family such as IL-1α and IL-1β and IL1R2, of the TNF/death receptor family such as TNF receptor II (TNFRSF1B), TRAIL (TNFSF10), and its decoy receptors, and a gene signature of IFN-α/β-regulated genes." (PMID 19884985, 2009).
multiple sclerosis (12 papers, 2011 to 2025). A progressive autoimmune disorder affecting the central nervous system resulting in demyelination. "TNFSF10 were suggested to be potentially associated with multiple sclerosis." (PMID 24932510, 2014). "TNFSF10 was significantly associated with multiple sclerosis." (PMID 24932510, 2014). "Blockade of TNFSF10 expressed in CD4+ myelin-specific T cells reduces caspase-dependent neuronal cell death in an experimental animal model for multiple sclerosis." (PMID 24932510, 2014). "The increasing expression of TNFSF10 was observed in peripheral blood mononuclear cells of patients with multiple sclerosis." (PMID 24932510, 2014). "The information retrieved from GeneCards showed there were six published studies reporting on the relationship between TNFSF10 and multiple sclerosis." (PMID 24932510, 2014). "Besides TNFSF10, the rest 7 genes showed markedly differential expression between multiple sclerosis patients and controls, appearing to be functionally related to apoptosis." (PMID 24932510, 2014). "Also, more than 80% of the top 30 most significant genes in multiple sclerosis were categorized into apoptosis signaling-related genes, and among them TNFSF10 was one of the significantly up-regulated genes." (PMID 24932510, 2014). "According to the GeneCards database, there were six published studies referring to the relationship between TNFSF10 and multiple sclerosis, indicating TNFSF10 might have an important role in multiple sclerosis." (PMID 24932510, 2014). "For example, it was reported that TNFSF10 is involved in pathogenesis of RA, SLE, AS, OA, and multiple sclerosis." (PMID 26352601, 2015). "Gene Ontology enrichment analysis revealed that TNFSF10 involved in the biological processes including protein kinase cascades, regulation of signal transduction and apoptosis, and the GPS1 and TRPS1 were primarily enriched in multiple sclerosis." (PMID 24932510, 2014).
diabetic nephropathy (11 papers, 2010 to 2025). "TNF‐related apoptosis‐inducing ligand (TRAIL, TNFSF10) is a cytokine belonging to the TNF superfamily that has been recently linked to the pathogenesis of diabetic nephropathy and lupus nephritis." (PMID 39492831, 2024). "Like other tumor necrosis factors, TNFSF10 is involved in induced apoptosis as well as in inflammation, and in humans its increased expression is linked to the pathogenesis of diabetic nephropathy." (PMID 30166318, 2018). "(a) TNFRSF11B and TNFSF10 are members of the tumour necrosis factor super family, which is known to be associated with diabetic kidney disease, lupus nephritis, and ANCA-associated glomerulonephritis." (PMID 21070623, 2010).
endothelial dysfunction (10 papers, 2020 to 2025). In vascular diseases, endothelial dysfunction is a systemic pathological state of the endothelium (the inner lining of blood vessels) and can be broadly defined as an imbalance between vasodilating and vasoconstricting substances produced by (or acting on) the endothelium. "We additionally identified three genes (JAK2, GBP1, and TNFSF10) whose mRNA transcription suppression by Lp299v in PBMCs was inversely correlated with brachial FMD% suggesting a potential more direct role for these proteins in inflammation-induced endothelial dysfunction in humans." (PMID 33597583, 2021).
esophageal cancer (10 papers, 2013 to 2023). A primary or metastatic malignant neoplasm involving the esophagus. "Frequent amplification of TNFSF10 was associated with the development and progression of esophageal cancer." (PMID 32095316, 2020).
fibrosarcoma (10 papers, 2003 to 2024). A malignant mesenchymal fibroblastic neoplasm affecting the soft tissue and bone. "In the liver, NK cells express the proapoptotic ligand TRAIL (TNFSF10), inhibiting metastasis formation of TRAIL-sensitive cancer cells, such as the fibrosarcoma cell line L929 and renal adenocarcinoma cell line Renca." (PMID 38506114, 2024).
Cirrhosis (8 papers, 2016 to 2025). A chronic disorder of the liver in which liver tissue becomes scarred and is partially replaced by regenerative nodules and fibrotic tissue resulting in loss of liver function. "Of the 21 ALT variants, 2 were directionally discordant with cirrhosis risk, specifically rs9663238 in HKDC1 and rs79287178 in TNFSF10, whereas all 20 GGT variants had concordant direction of effects with cirrhosis." (PMID 38632349, 2024).
dermatitis (8 papers, 2016 to 2025). An inflammatory process affecting the skin. "However, the importance of TRAIL in the clinical response to radiation and in its physiopathology was suggested by the association between two of the three reported TRAIL/TNFSF10 SNPs and acute and subacute radio-induced dermatitis." (PMID 26982083, 2016).
fibrosis (8 papers, 2018 to 2025). the formation of excess fibrous connective tissue in an organ or tissue in a reparative or reactive process. "In support of this are our observations that AAL(s) treated WT mice and Tnfsf10−/− mice were protected from bleomycin-induced fibrosis." (PMID 30732588, 2019).
lung diseases (8 papers, 2018 to 2025). "TNFSF10 is a protein functioning as a ligand that induces the process of cell death called apoptosis, but has also been implicated as a pathogenic or protective factor in various pulmonary diseases." (PMID 36518671, 2022).
metastatic carcinoma (8 papers, 2011 to 2021). A carcinoma which has spread from the original site of growth to another anatomic site. "These included genes which are implicated in inflammation and inflammatory responses to cancer (PTX3, IL8, TNFSF10, SERPINB13 and ANKRD1) and those involved in cell adhesion, cell migration and ECM degradation of importance in metastatic cancer (MMP12, MMP1 and ADAM19)." (PMID 28555042, 2017).